CXCL1 (C-X-C motif chemokine ligand 1)
Diseases named in the same sentence as CXCL1 in open-access papers (continued):
Sharing a sentence is not in itself a finding about the gene and the disease.
pulmonary fibrosis (9 papers, 2018 to 2024). Chronic progressive interstitial lung disorder characterized by the replacement of the lung tissue by connective tissue, leading to progressive dyspnea, respiratory failure, or right heart failure. "The genetic Cxcl1 deletion or pharmaceutical inhibition of Cxcl1 binding to Cxcr2 by Reparixin ameliorated the exacerbation of pulmonary fibrosis induced by particulate matter." (PMID 39768150, 2024). "Bleomycin-induced Cxcl1 production in lungs and Cxcl1 levels correlated with neutrophilic airway inflammation in mice preceding pulmonary fibrosis which were attenuated by the Cxcr2 antagonists or endothelial glycosaminoglycans antagonism." (PMID 39768150, 2024). "Particulate matter instillation increased the severity of bleomycin-induced pulmonary fibrosis and, depending on Cxcl1-mediated neutrophil chemotaxis, increased the severity of pulmonary fibrosis." (PMID 39768150, 2024). "In summary, CXCL1 critically mediates neutrophilic inflammation and angiogenesis in pulmonary fibrosis development." (PMID 39768150, 2024). "In our study, the increased expression of TIMP-1, CXCL1, MCP-1, MIP-2, and IL-1ra was strongly associated with RT-induced lung fibrosis through the induction of alternatively activated macrophages and neutrophils." (PMID 30347679, 2018). "Obese Nod2−/− mice had higher inflammatory cell infiltration in the bronchial alveolar lavage (BAL) and lungs, pulmonary fibrosis, mucus levels, hypertrophy and hyperplasia of goblet cells, M2 alveolar macrophage infiltration, interleukin-4 (IL-4), IL-5, IL-6, and lower CXCL1 and IL-22." (PMID 39507249, 2024). "Bleomycin increased the release of CXCL1 in the lung fibrosis model." (PMID 37266443, 2023). "It was observed that when CCL6 was neutralized in BLM-induced lung fibrosis, the expression levels of CCL3, CXCL1, CXCL2 and IL-1β were significantly reduced, indicating the effects of CCL6 on these chemokines and cytokine (sFigure 6B)." (PMID 36934284, 2023). "Similarly, in an established model of lung fibrosis, RP-832c significantly decreased lung fibrosis and significantly decreased inflammatory cytokines TNF-α, IL-6, IL-10, IFN-γ, CXCL1/2, and fibrosis markers TGF-β1 and MMP-13." (PMID 37174654, 2023).
renal cell carcinoma (9 papers, 2015 to 2024). "Also, a higher expression of CXCL1 in renal cell carcinoma tumors is associated with a worse prognosis for the patient." (PMID 38673949, 2024). "CXCL1 causes the recruitment of G-MDSCs to the tumor niche in renal cell carcinoma." (PMID 38673949, 2024). "A pro-inflammatory environment, particularly IL-1β, is responsible for CXCL1 expression in renal cell carcinoma." (PMID 38673949, 2024). "CXCL1 expression is positively correlated with the pathological stage of renal cell carcinoma." (PMID 38673949, 2024). "CXCL1 expression is increased relative to healthy tissue in renal cell carcinoma." (PMID 38673949, 2024). "CXCL1, along with other CXCR2 ligands, can cause renal cell carcinoma metastasis to the lung." (PMID 38673949, 2024). "The results demonstrated that the over expression of CXCL1 could promote the cell proliferation ability in renal cell carcinoma cells." (PMID 37927470, 2023). "CXCL1 may be involved in the appearance of renal cell carcinoma, as shown in experiments on mice." (PMID 38673949, 2024). "While human TNBC and renal cell carcinoma (RCC) cells express high levels of CXCR2 ligands including CXCL1 and CXCL2, a lack of CXCR2 expression by activated NK cells can limit their migration towards these tumors." (PMID 38022679, 2023).
tuberculosis (9 papers, 2016 to 2024). A chronic, recurrent infection caused by the bacterium Mycobacterium tuberculosis. "Therefore, we predicted central DEGs in the PPI network and noted strong interactions between TNF, IL-6, IL-10, IL-1β, CSF-2, IL-4, CXCL8, IFN-γ, IL-1α, and CXCL1, all of which are strongly associated with tuberculosis." (PMID 37818041, 2023). "CXCL1 serves as a new diagnostic biomarker for human TB, with a high sensitivity and specificity for both active tuberculosis (ATB) and latent tuberculosis (LTB)." (PMID 39337585, 2024). "High blood CXCL1 levels indicate that the patient will show a good response to treatment with anti-tuberculosis drugs." (PMID 36613652, 2022). "One of the components of tuberculosis pathogenesis is CXCL1." (PMID 36613652, 2022). "Thus, a baseline chemokine signature of CCL1/CXCL1/CXCL10 could serve as an accurate biomarker for the diagnosis of pediatric tuberculosis." (PMID 34635070, 2021). "The IL-17RA pathway was recently shown to be critical in CXCL1 and CXCL5-mediated early neutrophil recruitment after M. tuberculosis H37Rv infection." (PMID 27853279, 2016). "A recent prospective case-control study of children with and without tuberculosis found that baseline levels of CXCL1 and CXCL10 were exclusively higher in the infected people and decreased after anti-TB treatment." (PMID 36164329, 2022). "Our data showed that mycobacterium tuberculosis (Mtb)-specific IFN-γ, TNF-α, IL-2, IL-6, IL-10, IL-5, IP-10, IL-1Ra, CXCL-1 and MCP-1 responses based on QFT-Plus significantly differed between Mtb-infected (including ATB, LTBI and previous TB) and uninfected healthy populations." (PMID 38166667, 2024).
acute myeloid leukemia (8 papers, 2016 to 2025). Acute myeloid leukemia (AML) is a group of neoplasms arising from precursor cells committed to the myeloid cell-line differentiation. "CXC chemokines, particularly CXCL1, 8, 10, and 11, play roles in acute myeloid leukemia tumor processes." (PMID 39548525, 2024). "The CXCL5-Fc and CXCL1-Fc fusion proteins showed greater binding than the native chemokines to THP-1 cells, which are acute myeloid leukemia (AML) cells of myeloid origin and CXCR2-positive." (PMID 40427538, 2025). "A significant secretion of CCL3, CCL2, CCL4, CXCL1, and CXCL8 exists in acute myeloid leukemia (AML) cells." (PMID 40148973, 2025).
Anxiety (8 papers, 2015 to 2024). Intense feelings of nervousness, tension, or panic often arise in response to interpersonal stresses. "Similarly, chemokines such as ENA-78/CCL5, GROα/CXCL1, MCP-1/CCL2, and TARC/CCL17 were increased in women displaying high anxiety levels." (PMID 34863117, 2021).
chorioamnionitis (8 papers, 2019 to 2025). A morphologic finding indicating inflammation of the fetal sac membranes. "Indeed, both IL-6 and CXCL1 have been implicated in the pathogenesis of adverse pregnancy outcomes, including stillbirth, preterm labor, and chorioamnionitis, as has maternal infection/reinfection with naturally occurring AAV during pregnancy." (PMID 38950310, 2024). "CXCL1 is a potent chemokine responsible for neutrophil chemotaxis that has been implicated in significant intrauterine, placental, and fetal inflammation secondary to chorioamnionitis." (PMID 37396628, 2022). "Pregnant women with intra-amniotic infection have significantly higher amniotic fluid concentrations of CXCL1, and high CXCL1 levels correlate with maternal and newborn peripheral white blood cell counts." (PMID 31001130, 2019).
epilepsy (8 papers, 2020 to 2025). A brain disorder characterized by episodes of abnormally increased neuronal discharge resulting in transient episodes of sensory or motor neurological dysfunction, or psychic dysfunction. "CXCL11 levels and VEGFA levels increased the risk of epilepsy, CXCL1 levels, CXCL9 levels, IL-6 levels, TRAIL levels, and VEGFA levels were associated with an increased risk of FE and TTNFSF14 levels, VEGFA levels were associated with an increased risk of GE." (PMID 39315097, 2024). "Endothelial-specific Cdk5 knockout increased CXCL1 expression and led to progressive astrogliosis in epilepsy." (PMID 37280283, 2023). "The role of CXCL1, a murine ortholog of the human chemokine CXCL8 (IL-8), and its receptors CXCR1 and CXCR2 in epilepsy was discussed in a previous study using a murine model." (PMID 40243443, 2025). "In contrast to TNF-α and CXCL9, CXCL1 levels are not elevated in the cerebrospinal fluid of patients with epilepsy." (PMID 35457023, 2022). "CXCL1 does not seem to have the same role in epilepsy in humans as it does in mice." (PMID 35457023, 2022).
fungal infection (8 papers, 2015 to 2024). "After fungal infection, macrophages or DCs produce cytokines and chemokines, such as CXCL1 and GM-CSF to recruit neutrophils and macrophages to the infected area." (PMID 38166150, 2024). "After fungal infection, macrophages or DCs produce cytokines and chemokines, such as CXCL1 and granulocyte–macrophage colony-stimulating factor (GM-CSF), to recruit neutrophils and macrophages to the infected areas." (PMID 38166150, 2024). "After a fungal infection, macrophages or DCs produce cytokines and chemokines, such as CXCL1 and GM-CSF, to recruit neutrophils and macrophages to eliminate infections." (PMID 38166150, 2024). "We demonstrate that the transcription factor HIF-1α is crucial to orchestrate a proper immune response in this model and control fungal infection by regulating neutrophil recruitment and survival through the chemokine CXCL1." (PMID 36275017, 2022). "After fungal infection, macrophages produce cytokines and chemokines, such as CXCL1 and GM-CSF, to recruit neutrophils and macrophages to eliminate infections." (PMID 34301894, 2021). "The chemokine ligand CXCL1 plays a protective role in fungal infection through the recruitment of neutrophils." (PMID 32093731, 2020). "As TRAF1-deficiency was able to boost CXCL1 production in both macrophages and keratinocytes, we next generated bone marrow chimeric mice to address the cell type-specific role for TRAF1 in fungal infection." (PMID 32093731, 2020). "This suggests that the corneal epithelial cells can express more IL-1β, IL-6, IL-8 and CXCL1 after identifying the fungus, which resist the fungal infection and induce inflammatory cells infiltration to remove pathogenic fungi." (PMID 26036769, 2015). "First, lung and airway CXCL1 levels increase more rapidly than CXCL2 levels at the onset respiratory fungal infection and thus CXCR2-dependent trafficking steps may reflect the relative abundance of cognate ligands." (PMID 25621893, 2015). "Since the patient’s neutrophils did not exhibit a primary chemotaxis defect, we next measured levels of the neutrophil-targeted chemokines CXCL1, CXCL2, CXCL5 and IL-8 in the infected CSF by Luminex array at different prospective time-points during uncontrolled fungal infection." (PMID 26679537, 2015).
Hepatic steatosis (8 papers, 2019 to 2025). Steatosis is a term used to denote lipid accumulation within hepatocytes. "While inhibition of gut fungi or PGE2 synthase significantly inhibited hepatic PGE2, EP2, EP4, and chemokine (C-X-C motif) ligand 1 (CXCL1), and reduced the development of alcohol-associated hepatic steatosis." (PMID 39116092, 2024). "Recently, Cxcl1 overexpression in the livers of obese mice was shown to promote neutrophil infiltration and progression of fatty liver to NASH." (PMID 37895168, 2023). "It was observed that the level of liver PGE2 and the expression of EP2, EP4, CXCL1 were significantly reduced by antifungal treatments, accompanying with the amelioration on the hepatic steatosis." (PMID 33106075, 2020). "Interestingly, in Cluster 4 which was consistent with the progression of liver steatosis, DEGs were related to inflammation and included major cytokines and chemokines, such as Ccl2 and Cxcl1." (PMID 40687776, 2025). "Compared with the livers of patients with fatty liver, the livers of patients with NASH exhibit upregulated expression of neutrophil-recruiting chemokines, such as CXCL1 and their receptors (CXCR1 and CXCR2)." (PMID 37895168, 2023). "In addition, mice orally administrated with of PGE2 while fed with control diet also showed similar features of alcoholic hepatic steatosis and the increased expression of EP2 and CXCL1." (PMID 33106075, 2020). "Furthermore, WTD-induced hepatic steatosis, pro-inflammatory gene expression (MCP-1 and CXCL1) and immune cell infiltration as well as activation of hepatic stellate cells (HSC) and expression of collagen alpha I were significantly reduced in the livers of s-XN-treated mice compared to WTD controls." (PMID 30999670, 2019).
Hepatitis (8 papers, 2017 to 2025). Inflammation of the liver. "Proinflammatory cytokines released from activated T cells and macrophages, including TNF-α, IFN-γ, IL-6, and CXCL1, are critical in ConA-induced hepatitis." (PMID 40092485, 2025). "In order to investigate the induction of cytokines before the peak of LCMV-induced hepatitis, we quantified protein concentrations of chemokine (C-X-C motif) ligand 1 (CXCL1), interleukin 6 (IL-6) and interferon alpha (IFNα) in sera of WT and Trem2−/− mice by ELISA." (PMID 28900132, 2017). "Immature neutrophils circulating in advanced MASH patients also expressed an array of pro-inflammatory chemokines that can aggravate and perpetuate liver inflammation, such as CCL2, CCL3, CCL5, CXCL1, and XCL2." (PMID 38791066, 2024). "Our study demonstrated that APAP and ROX co-treatment significantly increased the expression levels of TNF-α, INF-γ, VCAM-1, CXCL-1, STAT-3, Nrf-2, GSTA, GCLC-1, HO-1 and NQO1, suggesting that APAP and ROX co-treatment can induce liver inflammation." (PMID 32132876, 2020). "The liver transcriptional expressions of CXCL1, CXCL2, CXCL3, CXCL5, CCL2, and CCL6 significantly increased in WT and IL-33 KO mice during L2-MHV3-induced hepatitis compared to those in control PBS-injected mice as soon as 48 h PI and at 72 h PI." (PMID 28607531, 2017). "We observed that SHP deficiency in hepatocytes led to the increased secretion of CXCL2, but not CXCL1, upon TNFα stimulation, emphasizing that hepatocytes contribute to increased levels of circulating CXCL2 in Shp KO mice during ConA-induced hepatitis." (PMID 30323351, 2018).
kidney damage (8 papers, 2012 to 2024). "Up-expression of CXCL1 exacerbates fibrosis mediated kidney damage, and inhibition of CXCL1 - CXCR2 shaft can greatly relieve kidney inflammation." (PMID 37266443, 2023). "Within a mouse model of UA-induced nephropathy, CXCL1 was significantly upregulated in renal tubules and promoted inflammatory responses." (PMID 34385934, 2021). "C-X-C motif chemokine ligand 1 (CXCL1) was upregulated in renal tubules from mice subjected to uric acid (UA)-induced nephropathy." (PMID 34385934, 2021). "It is hypothesized that CXCL1 may be upregulated in conjunction with immune complex deposition and occurs prior to cellular infiltration, proteinuria and kidney damage by binding to the CXCR2 receptor in mesangial cells or glomerular cells." (PMID 34961474, 2021). "We demonstrated that Lin28A OE in non-hematopoietic lineage can trigger an inflammatory response via the rapid upregulation of several cytokines, including CXCL1 and CCL2, leading to severe kidney damage." (PMID 39113694, 2024). "Moreover, CXCL1, CXCL9, β-NGF, C-peptide, GIP and adiponectin are higher only in CHC patients in agreement with previous studies in which these molecules were found elevated only in diabetic patients with complications (nephropathy, retinopathy and atherosclerotic lesions)." (PMID 22745767, 2012). "While serum levels of IFN-γ, IL-2, IL-4, and IL-12 did not display a difference between experimental groups (data not shown), expression of IL-5, IL-6, TNF-α, IL-10, CXCL1, and IL-1β was elevated in the NZM2410/J mice displaying signs of severe kidney damage." (PMID 28491039, 2017).
mastitis (8 papers, 2015 to 2024). Inflammation of breast tissue during lactation or postpartum due to an obstructed duct or infection. "In particular, highly virulent mastitis pathogens caused a profound induction of the chemokines CXCL1 and CCL2 as well as the neutrophil growth factor G-CSF." (PMID 29988549, 2018). "Based on the findings obtained in this investigation, high levels of G-CSF and CXCL1 may accompany severe, systemic bacterial infection, and it is, thus, possible that levels of G-CSF and/or CXCL1 may be useful diagnostic criteria in mastitis." (PMID 27713743, 2016). "It has been suggested that CXCL1 can be used as therapeutic targets, therapeutics, or biomarkers in mastitis." (PMID 29470489, 2018). "In agreement with a role of this chemokine in mastitis, CXCL1 is detectable at the protein level in the bovine mammary gland in response to intramammary lipoteichoic acid (LTA) infusion." (PMID 27713743, 2016). "Moreover, the levels of these compounds correlated significantly with clinical outcome, suggesting the possibility to further evaluate G-CSF and CXCL1 as therapeutic targets, therapeutics, or biomarkers in mastitis." (PMID 27713743, 2016). "Overall, the observed role of endogenous cathelicidin promoting Cxcl-1 in protothecal mastitis could be critical in attracting leukocytes early to sites of infection and retain macrophages into the udder during the innate immune response against pathogenic algae." (PMID 32117805, 2020). "TLR2, NOD2, and inflammatory cytokines (TNF-α, IL-1β, IL-6, CXCL1, IL-10, TGF-β1, and IFN-γ) are involved in the response to mastitis induced by S. aureus." (PMID 25990971, 2015). "In this study, we found that SAMC suppressed the secretion of IL-6 as well as Il6, Tnf, Cxcl1, and Ccl2 mRNA levels induced by LPS in HC11 cells, suggesting that SAMC is a key component of AGE that modulates the immune response in an in vivo mastitis model." (PMID 39609525, 2024). "As previously reported in other tissues, CXCL1 (KC), CXCL2 (MIP2), ICAM-1, ACKR1, Selp (P-selectin), and Itgam (Cd11b), are all most probably involved in transendothelial neutrophil trafficking in mastitis." (PMID 37032878, 2023).
prostate tumor (8 papers, 2013 to 2026). "CXCL1 acts on CXCR2+ macrophages in the tumor niche in prostate tumors, which causes stronger M2 polarization of these cells." (PMID 37108425, 2023). "The level of this chemokine in prostate tumors is dependent on an autocrine increase in CXCL1 expression." (PMID 37108425, 2023). "Obese patients have high CXCL1 expression in prostate tumors; in contrast, lean patients rarely have high CXCL1 expression in these tumors." (PMID 37108425, 2023). "The levels of CXCL1 in prostate tumors are higher in T-stage and N-stage tumors than in earlier stages." (PMID 37108425, 2023). "Although CXCL1 has been reported to suppress malignancy by limiting prostate tumor metastasis and reinforcing growth arrest, many reports indicate that CXCL1 promotes cancer progression." (PMID 24376747, 2013). "In one exceptional report, CXCL1 overexpression acted as a suppressor of malignancy by limiting the escape of prostate tumor cells from the primary tumor and reinforcing growth arrest." (PMID 24376747, 2013). "Similarly, several studies have linked marrow fat cells-derived CXCL1 and CXCL2 chemokines with prostate tumor progression and the effects of osteolysis in metastatic prostate cancer." (PMID 35498437, 2022). "The baseline and radiation-enhanced secretion of CXCL8 (and its orthologues CXCL1, CXCL2 and CXCL5) from PTEN-deficient prostate tumour epithelial cells exerts both autocrine and paracrine actions within the tumour microenvironment given the expression of CXCR1 and CXCR2 upon multiple cell types." (PMID 32743555, 2020). "CXCL1 has been shown to be released by human and mouse PCa cells and, acting via its CXCR1 receptor, facilitates recruitment of ASCs into prostate tumors." (PMID 41450167, 2026). "Taken together, these results suggest that HFD-induced increases in the production of soluble factors (MCP-1, CXCL1, CXCL2, and CXCL13) play important roles in the stimulation of prostate tumor progression in mice." (PMID 25912035, 2015).